ASS1 (argininosuccinate synthase 1)
Diseases named in the same sentence as ASS1 in open-access papers (continued):
Sharing a sentence is not in itself a finding about the gene and the disease.
cancer (continued). "The study using in vitro assays identified a synthetic lethal dependence between ASS1 deficiency and polyamine metabolism, which could be exploited for treating ASS1-negative cancers." (PMID 37445845, 2023). "ASS1 deficiency is linked in general to more aggressive cancer biology and worse clinical outcomes." (PMID 36903394, 2023). "In fact, a previous study showed that an Ass1 deficiency increases uracil in cancer cells." (PMID 35705545, 2022). "Indeed, urea cycle dysregulated cancers, with functional loss of ASS1, have been linked to favourable genetic and biochemical signatures associated with increased responsiveness to immune checkpoint blockade." (PMID 35466524, 2022). "Re-expression of ASS1 in ASS1-deficient cancers stopped tumor growth and development." (PMID 36232732, 2022). "Since arginine is required by a variety of cancer cells, especially those that are highly proliferating, therapeutic arginine deprivation in ASS1-deficient cancers has been examined as a potential anticancer strategy in a number of tumor types, including our own studies in GBM." (PMID 35113813, 2022). "We did not observe antitumor activity of ADI‐PEG 20 and PLD similar to that in previous clinical studies of ADI‐PEG 20 combined with other chemotherapeutic agents, which induced effective doubling of the response rate in patients with ASS1‐deficient malignant tumors." (PMID 34841717, 2022). "Taken together, the data support the hypothesis that arginine depletion might potentiate the cytotoxic effects of certain chemotherapeutics in both ASS1-proficient and deficient cancers." (PMID 33674736, 2021). "ASS1 regulation may thus define the susceptibility of stem-like or differentiated cancer cells towards therapies targeting arginine biosynthesis." (PMID 33809510, 2021). "Aspartate exhaustion is one reason arginine-deprivation causes the death of ASS1-low cancer cells." (PMID 34298755, 2021). "ASS1 expression by cancer cells was significantly linked with better prognosis (p = 0.0007)." (PMID 34344457, 2021). "Importantly, loss of ASS1 expression renders cancer cells dependent on extracellular arginine, as de novo arginine synthesis is reliant on ASS14." (PMID 32814773, 2020). "Similarly, arginine deprivation promoted autophagy as a means of survival in ASS1-deficient cancers." (PMID 27683125, 2016). "ASS1-deficient cancers rely on extracellular arginine, due to arginine auxotrophy." (PMID 27683125, 2016). "In addition, although ASS1 loss has been identified as a potential indicator of arginine auxotrophy in cancer, its regulation is complex and its use as a biomarker in combination therapy is unfamiliar." (PMID 25164070, 2014). "Moreover, incorporating immunohistochemical ASS1 staining into the diagnostic workflow for biopsies and tumor specimens could enhance the personalization of anti-cancer treatments, paving the way for more targeted and effective therapeutic strategies." (PMID 41300990, 2025). "Therefore, it is unknown whether the lack of cell death resulting from arginine starvation is due to metabolic adaptation, mitochondrial alteration, or alterations in the apoptotic machinery in ASS1-deficient cancers." (PMID 39898973, 2025). "ASS1 deficiency confers a critical dependency on extracellular arginine, and it is therefore vital to recognise how depletion of arginine may impact these ASS1 “low” cancers." (PMID 36903394, 2023). "Studies have also shown that low ASS1 expression is associated with poor prognosis and resistance to conventional chemotherapy in various types of cancer, indicating that alternative therapeutic strategies such as arginine deprivation therapy may be necessary for these patients." (PMID 37445845, 2023).
cancer (continued). "In particular, low ASS1 combined with high citrin (mitochondrial aspartate transporter) expression conferred poor survival outcomes in both adenocarcinoma and squamous cell lung cancer consistent with the redirection of aspartate for enhanced pyrimidine synthesis in urea cycle‐deficient cancers." (PMID 34382365, 2021). "Indeed, DFMO plus ADI-PEG20 combination treatment has synergistic effects, which could be exploited for treatment of ASS1-deficient cancers." (PMID 34068137, 2021). "Similarly, targeting glutamine metabolism through GLS inhibition could provoke the lethality of ASS1-deficient cancers and is currently being evaluated in GIST and NF1-mutated cancers." (PMID 34294128, 2021). "Similarly, several cancers are deficient for the urea cycle enzyme, argininosuccinate synthase (ASS1), which appears to be a metabolic advantage by diverting aspartate into de novo pyrimidine synthesis, but renders ASS1-deficient cancer cells auxotrophic for arginine." (PMID 34256164, 2021). "Among the deregulated proteins, we identified known cancer proteins, such as the tumor suppressors ASS1 and ABI3, which were downregulated in our model, or specifically upregulated TRBC1." (PMID 41715231, 2026). "In cancer cells, the UC is reconfigured/reorchestrated to support high anabolic demand, often involving the dysregulation of key enzymes such as ASS1, ASL, OTC and CPS1." (PMID 42074106, 2026). "Arginine is a semi-essential amino acid whose production in many cancer cells is inhibited by the suppression of Argininosuccinate Synthase 1 (ASS1), a key enzyme in arginine biosynthesis." (PMID 41190243, 2025). "One of the most promising metabolic‐targeted cancer therapies involves arginine depletion using pegylated arginine deiminase (ADI‐PEG20) or pegargiminase, which specifically targets ASS1‐deficient tumors." (PMID 40552664, 2025). "The expression profile of ASS1 demonstrates remarkable heterogeneity across various cancer types, which fundamentally dictates their arginine auxotrophic phenotypes." (PMID 41216870, 2025). "The dynamic interplay between CLOCK and ASS1 not only highlights the importance of temporal control in cellular metabolism but also reveals potential therapeutic targets for cancer and vascular disorders." (PMID 41295280, 2025). "Cancers that lack the urea cycle and tumor suppressor enzyme argininosuccinate synthetase 1 (ASS1) are inherently vulnerable to amino acid deprivation techniques and rely heavily on arginine for survival." (PMID 40227645, 2025). "Paradoxically, upon arginine deprivation, resurgence of ASS1 has been reported and considered a direct mechanism of acquired resistance of cancer to therapy." (PMID 40253325, 2025). "ASS1, the key enzyme during arginine synthesis, was downregulated in ccRCC patients’ biopsy samples, indicating an arginine dependency in cancer cells." (PMID 40933888, 2025). "ASS1-negative cancers are thought to respond better to arginine deprivation therapy than tumors with low ASS1 expression." (PMID 41267750, 2025). "To validate the role of NMFs’ secreted arginine in rescuing the cancer cells’ survival under arginine deprivation, we silenced the expression of ASS1 in NMFs co-cultured with cancer cells." (PMID 41511309, 2025). "Apart from the essential role in arginine metabolism, ASS1 has multiple functions in cancer biology." (PMID 41460862, 2025). "So, ASS1 silencing promotes cancer mutagenesis, which facilitates the adaptability potential of cancer cells." (PMID 41300990, 2025). "To date, ADI-PEG20 has been indicated primarily as a potential treatment for ASS1-ve and arginine-auxotrophic cancers." (PMID 39758821, 2025). "Downregulation of ASS1 is correlated with worse patient survival in various cancers, including non-small-cell lung cancer and nasopharyngeal carcinoma." (PMID 41300990, 2025). "This ASS1 silencing conjointly benefits cancer cells in terms of DNA damage adaptation, releasing serine synthesis, and promoting chemotherapy resistance." (PMID 40253325, 2025).
cancer (continued). "Taken together, in ASS1-deficient cancer, EI24 elevated ASS1 expression and activity thus sustained cell viability upon arginine depletion condition." (PMID 40253325, 2025). "Many cancers downregulate ASS1, rendering them arginine-auxotrophic and sensitizing them to arginine-depleting agents." (PMID 41511309, 2025). "By first focusing on the cancer cells within the tumor, we confirmed that Ass1 expression levels were reduced in cancer cells of the KD and KD + AFD groups and elevated in the AFD group." (PMID 41511309, 2025). "A publicly available database, The Cancer Genome Atlas has been used to assess gene expression patterns of ASS1 for given types of cancer and these levels were found to correlate with the extent of arginine auxotrophy." (PMID 39920310, 2025). "Herein, we report the enhanced regulation of ASS1 protein translation in cancer cells upon arginine starvation, interestingly via a novel function of etoposide-induced protein 2.4 homolog (EI24)." (PMID 40253325, 2025). "A potential explanation for why cancer cells repress ASS1 and become dependent on an exogenous source of arginine is that ASS1 consumes aspartate." (PMID 39920310, 2025). "Silencing ASS1 in cancer cells has been shown to suppress the urea cycle and redirect available aspartate into pyrimidine biosynthesis." (PMID 41295280, 2025). "Conversely, in certain cancers such as pancreatic cancer and hepatocellular carcinoma, ASS1 is found to be downregulated, indicating diverse regulatory mechanisms in different malignancies." (PMID 38338444, 2024). "The metabolism alteration in these cancers is primarily evidenced by the suppression of argininosuccinate synthase 1 (ASS1), a crucial enzyme in arginine synthesis." (PMID 38756774, 2024). "Broadly, our findings propose additional mechanisms by which the downregulation of ASS1 in cancers promotes carcinogenesis and survival." (PMID 38858597, 2024). "Downregulated arginosuccinate synthase 1 (ASS1) was considered a tumorigenesis characteristic, promoting the proliferation of many cancers, including breast cancer and renal cancer." (PMID 39585048, 2024). "In our earlier research, we discovered that activating ASS1 with an activator can suppress cancer growth by decreasing pyrimidine synthesis." (PMID 38710705, 2024). "In such cases, arginine deprivation strategies have been explored as potential therapeutic approaches, as they can selectively target cancer cells that lack ASS1 expression while sparing normal cells that can produce arginine through the biosynthesis pathway." (PMID 39330508, 2024). "It had been known that some human cancers had low expression of argininosuccinate synthase 1 (ASS1)." (PMID 36798123, 2023). "LncRNA00312 was low expressed in RCC, and inhibited the proliferation and invasion of cancer cells in vitro by elevating ASS1." (PMID 36969848, 2023). "Multiple studies have also shown that cancer cells reactivate ASS1 expression and arginine biosynthesis when extracellular arginine becomes limited to support tumor growth." (PMID 37254839, 2023). "Downregulation of ASS1 expression promotes cancer proliferation by diversion of its aspartate substrate toward the pyrimidine synthesis pathway." (PMID 36984849, 2023). "Together, these data provide a key mechanistic explanation for other studies that reduced ASS1 protein expression drives and increases tumorigenesis and poor-prognosis cancers." (PMID 36903394, 2023). "It has been well documented that ASS1 expression is differentially regulated in different types of cancer." (PMID 36998052, 2023). "ASS1 is often silenced in cancers, including MPM, conferring reliance upon extracellular arginine, and hence susceptibility to arginine deprivation using ADI-PEG20." (PMID 36669126, 2023). "ASS1 expression in some cancer cells is silenced when exogenous arginine is available, as arginine synthesis can otherwise slow the proliferation of cancer cells." (PMID 37254839, 2023).
cancer (continued). "Our first pan-cancer study offers a relatively comprehensive understanding of the roles of ASS1 in different tumors." (PMID 38053661, 2023). "In conclusion, our first pan-cancer analysis of ASS1 showed that the expression of ASS1 in most tumors was different from that in normal tissues, and was statistically correlated with clinical prognosis and immune cell infiltration across multiple tumors." (PMID 38053661, 2023). "Growing evidence indicates that many cancers inactivate urea cycle enzymes, including ASS1, so the L-aspartate is available for nucleotide synthesis." (PMID 38283944, 2023). "In many cancer types, ASS1 expression is epigenetically downregulated and the low ASS1 levels correlated with poor survival in patients." (PMID 36998052, 2023). "We observed downregulation of arginosuccinate synthase 1 (ASS1) on a proteomic level, which is proposed to preserve aspartate levels in cancer cells for use in biosynthetic pathways." (PMID 37063293, 2023). "Other worth-mentioning genes and metabolites previously reported in cancer progression are ASS1, CAT, ALDH7A1, arginine, glutamine, BCAAs, and AAAs." (PMID 37999208, 2023). "The silencing of the ASS1 gene that encodes the rate-limiting enzyme in the urea cycle and arginine auxotrophy resulting from the silencing of ASS1 are common metabolic alterations in many cancers." (PMID 38053661, 2023). "Although ADI therapy exhibited promising results, several studies in cancer have reported that this therapy inevitably triggers ADI resistance through induction of ASS1 expression and activation of alternate signaling pathways in ASS1-negative cells." (PMID 37194070, 2023). "Accordingly, it is essential to perform a global analysis of ASS1 in tumors to understand the metabolic pathways and enzymes involved in the synthesis of arginine metabolites when it comes to cancer therapy." (PMID 38053661, 2023). "According to the expression levels of ASS1, we divided the cancer cases into high-expression and lower-expression groups, and used TCGA and GEO datasets to study the correlation between ASS1 expression and the prognosis of different tumor patients." (PMID 38053661, 2023). "Its efficacy can be attributed to its ability to induce cell death in cancer cells that lack the essential enzyme ASS1 for arginine synthesis." (PMID 37445845, 2023). "Ectopic expression of the ASS1 gene in cancer cells inhibits their growth, indicating its role as a tumor suppressor enzyme." (PMID 38283944, 2023). "In some cancers, high ASS1 is associated with poor prognosis; however, like BAP1 loss, elevated ASS1 is associated with better OS in patients with MPM." (PMID 36669126, 2023). "Studies on cancer cells with low levels of ASS1 that were denied arginine contributed to the current understanding of the impact of arginine on cancer metabolism." (PMID 38248814, 2023). "Arginine depletion is one of the therapeutic approaches for cancer, which requires the identification of the status of ASS1." (PMID 38053661, 2023). "It has been proposed that the suppression of ASS1 induces arginine auxotrophy, sensitizing cancer cells to arginine depletion." (PMID 36539415, 2022). "Alternatively, an arginine-independent ASS1 effect can be taken advantage of in developing cancer therapeutics." (PMID 35887124, 2022). "ASS1 levels in cancer are differentially regulated under various environmental conditions to metabolically benefit cancer progression." (PMID 35898872, 2022). "For example, ASS1 is downregulated under acidic conditions, and ASS1-depleted cancer cells maintain a higher intracellular pH, depend less on extracellular glutamine, and display higher glutathione levels." (PMID 35898872, 2022). "In this review, we summarize the current knowledge of expression pattern of ASS1 and related signaling pathways in cancer and the potential role as a novel therapeutic target in cancer." (PMID 35910381, 2022).
cancer (continued). "Many types of cancer cells, especially HCC, are deficient in argininosuccinate synthase 1 (ASS1), which is a rate-liming enzyme for arginine regeneration." (PMID 35955521, 2022). "In general, the downregulation of ASS1 is mediated by promoter methylation or hypoxia-inducible factor (HIF) 1α in multiple cancers." (PMID 35898872, 2022). "Cancer cells in an acidic or hypoxic environment downregulate the expression of the urea cycle enzyme ASS1, which provides them with redox and pH advantages, resulting in better survival." (PMID 35898872, 2022). "In this review, we summarize the current knowledge of expression pattern of ASS1 and related signaling pathways in cancer and its potential role as a novel therapeutic target in cancer." (PMID 35910381, 2022). "This further highlights the importance of tissue lineage as a critical determinant of ADI‐PEG20 sensitivity in arginine‐dependent cancers as assessed by ASS1 immunohistochemistry alone." (PMID 35466524, 2022). "Cancer cells are dependent on extracellular arginine because of the decreased expression of arginine-synthesizing enzymes, argininosuccinate synthase (ASS1) and argininosuccinate lyase (ASL)." (PMID 35898872, 2022). "Actually, the method of reconstructing the activity or expression of ASS1 in cancer cells is particularly important for tumor therapy." (PMID 35674458, 2022). "As illustrated in previous review, ASS1 and arginine metabolism represent compelling molecular targets for cancer management." (PMID 35910381, 2022). "This is consistent with previous data on epigenetic silencing of ASS1 as a mechanism mediating arginine auxotrophy in cancer cell lines and primary tumours." (PMID 35466524, 2022). "Several cancer types are characterized by low ASS1 expression, including malignant melanoma, hepatocellular carcinoma, mesothelioma, and prostate cancer." (PMID 34599156, 2021). "One of the challenges in ADI-based therapy is the development of intrinsic resistance by the upregulation of ASS1 in treated cancer cells." (PMID 33664852, 2021). "The promising prospect of using arginine deprivation to starve cancer cells to death has in recent years, fueled the preclinical studies, in vitro (cell lines) and in vivo (xenografts) on a variety of ASS1-low tumors." (PMID 34298755, 2021). "Much of our current understanding of the arginine effects on cancer metabolism is derived from arginine-deprivation studies of ASS1-low cancer cells." (PMID 34298755, 2021). "Previous reports showed that cisplatin sensitivity is restricted during cancer in an ASS1- expression–dependent manner." (PMID 33838671, 2021). "In particular, argininosuccinate synthase 1 (ASS1), the rate-limiting enzyme for endogenous arginine de novo synthesis, is silenced in up to 90% of cancer, rendering cancer cells arginine auxotrophic." (PMID 33594058, 2021). "A common mechanism is the restoration or upregulation of ASS1 expression to provide much-needed arginine in starved cancer cells." (PMID 34298755, 2021). "Our studies and the data in literature support that ASS1 functions as a tumor suppressor in those types of cancers whose ASS1 expression is down-regulated." (PMID 33859183, 2021). "Meanwhile, the silencing of the ASS1 enzyme in cancer cells supports their proliferation by activating carbamyl phosphate synthase-2, aspartate transcarbamylase, and the dihydrotransaminase complex, which promote pyrimidine synthesis." (PMID 33598460, 2021). "We further found that SPA or LM-2I pre-incubated with ASS1 recombinant protein had significantly less toxicity to cancer cells than the same concentration of SPA or LM-2I." (PMID 33859183, 2021). "ASS1 expression by cancer cells was noted in 75 cases (76.5%), ranging from 10 to 100% (median 40%)." (PMID 34344457, 2021). "Arginine starvation by using arginine-metabolizing enzymes such as arginase, arginine decarboxylase and arginine deiminase (ADI) has received increasing attention as an intervention to treat ASS1-low cancers." (PMID 34158865, 2021).